SLC8A2 (solute carrier family 8 member A2)
Description:
Mediates the electrogenic exchange of Ca(2+) against Na(+) ions across the cell membrane, and thereby contributes to the regulation of cytoplasmic Ca(2+) levels and Ca(2+)-dependent cellular processes. Contributes to cellular Ca(2+) homeostasis in excitable cells. Contributes to the rapid decrease of cytoplasmic Ca(2+) levels back to baseline after neuronal activation, and thereby contributes to modulate synaptic plasticity, learning and memory. Plays a role in regulating urinary Ca(2+) and Na(+) excretion.
Synonyms: KIAA1087; NCX2
Tractability: Antibody: its Gene Ontology location is reachable by antibodies, with high confidence; UniProt places it where antibodies can reach, with medium confidence; UniProt predicts a signal peptide or a membrane-spanning region. PROTAC: its protein half-life has been measured.
Gene: Protein-coding gene on chromosome 19 (47,428,017 to 47,471,918, reverse strand). Ensembl gene ENSG00000118160.
Subcellular location: Cell membrane; Basolateral cell membrane; Perikaryon; Cell projection, dendrite; Cell projection, dendritic spine
Pathways (Reactome):
Hemostasis: Reduction of cytosolic Ca++ levels
Muscle contraction: Ion homeostasis
Transport of small molecules: Sodium/Calcium exchangers
Gene Ontology:
Molecular function: calcium ion transmembrane transporter activity; calcium:monoatomic cation antiporter activity involved in regulation of postsynaptic cytosolic calcium ion concentration; calcium:sodium antiporter activity; sodium ion transmembrane transporter activity
Biological process: calcium ion export across plasma membrane; calcium ion transmembrane transport; cognition; intracellular calcium ion homeostasis; learning; learning or memory; long-term synaptic potentiation; memory; modulation of excitatory postsynaptic potential; neuron cellular homeostasis; positive regulation of intracellular signal transduction; regulation of action potential firing pattern; regulation of calcineurin-mediated signaling; regulation of cardiac conduction; regulation of cytosolic calcium ion concentration; regulation of gene expression; regulation of short-term neuronal synaptic plasticity; response to ischemia; sodium ion transmembrane transport; synapse organization; transport across blood-brain barrier; calcium ion transport; cell communication; regulation of postsynaptic cytosolic calcium ion concentration; transmembrane transport
Cellular component: presynapse; axon; axon terminus; dendrite; neuronal cell body; perikaryon; plasma membrane; postsynapse; postsynaptic density; sarcolemma; synapse; basolateral plasma membrane; dendritic spine; membrane
Genetic constraint (gnomAD): Loss-of-function variants: 13 observed, 61.99 expected, observed/expected ratio (o/e) 0.21, 90% interval 0.14 to 0.33. The upper end of that interval is the gene's LOEUF score, 0.33, which puts it in group 1 of 6, group 1 being the genes least tolerant of losing a copy. Missense variants: 764 observed, 1,210.2 expected, observed/expected ratio (o/e) 0.63, 90% interval 0.59 to 0.67. Synonymous variants: 571 observed, 545.96 expected, observed/expected ratio (o/e) 1.05, 90% interval 0.98 to 1.12.
Homologues: Orthologues: chimpanzee SLC8A2 (100% identical), macaque SLC8A2 (99% identical), dog SLC8A2 (98% identical), pig SLC8A2 (98% identical), rat Slc8a2 (97% identical), mouse Slc8a2 (94% identical), guinea pig SLC8A2 (90% identical), tropical clawed frog slc8a2 (75% identical), zebrafish slc8a2b (71% identical), zebrafish slc8a2a (64% identical), Caenorhabditis elegans ncx-3 (32% identical). Paralogues in human: SLC8A3 (69% identical), SLC8A1 (67% identical), ADGRV1 (31% identical), FREM2 (21% identical), FREM3 (17% identical), FRAS1 (17% identical), FREM1 (17% identical).
Diseases named in the same sentence as SLC8A2 in open-access papers:
SLC8A2 is named in the same sentence as 30 diseases in open-access papers, as found by Europe PMC text mining. Sharing a sentence is not in itself a finding about the gene and the disease. The quoted sentences say what the papers report.
glioma (7 papers, 2011 to 2023). A benign or malignant brain and spinal cord tumor that arises from glial cells (astrocytes, oligodendrocytes, ependymal cells). "SLC8A2 is encoded on chromosome 19q13.3, and loss of heterozygosity at 19q13.3 is both a common genetic change in human gliomas and a prognostic marker for predicting overall survival." (PMID 25749033, 2015). "SLC8A2 (solute carrier family 8, member 2 gene, encoding Na+/Ca2+ exchanger) might play a role in gliomas, the most common type of adult primary brain tumors, which have very low survival rates." (PMID 32878087, 2020). "Our identification of SLC8A2 as a bivalent tumor suppressor gene supports the argument that SLC8A2 is a good target for therapy in glioma." (PMID 25749033, 2015). "Based on this observation, it has been hypothesized that SLC8A2 may be a possible tumor suppressor gene, and thus important for glioma development." (PMID 32878087, 2020). "In glioma cells, SLC22A18, SLC8A2, SLC9A1, and SLC34A2 were examined as the risk genes of glioma." (PMID 32565801, 2020). "An analysis of the epigenetic regulation of SLC8A2 in glioma has been performed previously." (PMID 25749033, 2015). "Interestingly, SLC8A2 is found silenced by methylation in human gliomas where it has been proposed to act a tumor suppressor gene." (PMID 21931769, 2011). "Studies on GB have further shown that the cell cycle progression and in vitro proliferation of U87MG glioma cells is not affected by SLC8A2." (PMID 37298344, 2023). "The methylation patterns explained the down-regulation of SLC8A2 in gliomas, which could not be detected at any significant level." (PMID 25749033, 2015). "On the other hand, SLC8A2 is possibly a common regulator of endothelium-dependent and non-dependent U87MG cell angiogenesis, ultimately affecting glioma angiogenesis." (PMID 37298344, 2023). "Moreover, the study suggests that SLC8A2 is possibly a common regulator of endothelium dependent and non-dependent U87MG cell angiogenesis, ultimately affecting glioma angiogenesis." (PMID 37298344, 2023).
breast carcinoma (3 papers, 2011 to 2021). "However, we have now shown that the expressions of SLC8A2 and PLLP were upregulated in metastasizing breast cancer and melanoma cells in the brain." (PMID 28210624, 2017).
Parkinson disease (2 papers, 2020 to 2025). A progressive degenerative disorder of the central nervous system characterized by loss of dopamine producing neurons in the substantia nigra and the presence of Lewy bodies in the substantia nigra and locus coeruleus. "In this context, SLC8A2 and SLC8A3 have even been proposed as new molecular targets in Parkinson’s disease and potential targets for therapeutic strategies." (PMID 32326436, 2020).
intellectual disabilities (1 paper, 2017). "The deletion of chromosome 19q13.32, which harbors the slc8a2 gene, results in the occurrence of intellectual disabilities, facial asymmetry and oculomotor paralysis." (PMID 28650979, 2017).
tumor (9 papers, 2011 to 2025). "The SLC8A2 gene acts as a tumor suppressor and inhibits the invasion, growth, and angiogenesis of glioblastomas." (PMID 39006025, 2024). "In addition, SLC8A2, which is a member of the solute carrier family 8, is a tumor suppressor gene of GBM and shows a difference in the survival rate, according to the expression level in OD of TCGA." (PMID 32906679, 2020). "Finally, we showed that SLC17A7 and SLC8A2 are two bivalent tumor suppressor genes whose expression were down-regulated in GBM tissues compared with normal brain tissues." (PMID 25749033, 2015). "The calcium signaling pathway (hsa04020) contained 23 genes (p = 8.81 × 10−7), including key receptors such as SLC8A2, HTR2C, GRIN1, CACNA1I, and GRIN2B, which regulate intracellular calcium levels and tumor microenvironment dynamics via glutamate interactions." (PMID 40406701, 2025).
SLC8A2 also shares sentences with these, for which no sentence is quoted: brain ischemia (5 papers); cancer (4); glioblastoma (3); Alzheimer disease (2); Cerebral ischemia (2); colon cancer (2); neurological diseases (2); osteosarcoma (2); Stroke (2); amyotrophic lateral sclerosis (1); Anxiety (1); asthenia (1); cognitive decline (1); depression (1); heart disease (1); infarction (1); ischemia (1); lymph node metastasis (1); melanoma (1); multiple sclerosis (1); neuropathies (1); oculomotor paralysis (1); polyp (1); pulmonary hypertension (1); spinal muscular atrophy (1).